OPTN (optineurin)
Diseases named in the same sentence as OPTN in open-access papers (continued):
Sharing a sentence is not in itself a finding about the gene and the disease.
amyotrophic lateral sclerosis (continued). "Amyotrophic lateral sclerosis (ALS) is a progressive debilitating condition where the loss of spinal motor neurons leads to paralysis and death, and researchers have also found mutations in OPTN to be associated with various forms of this disease." (PMID 25329564, 2014). "The preliminary version of the algorithm described here has been used to prove that the SLC34A2 gene is responsible for pulmonary alveolar microlithiasis; the current version has been used to show that the OPTN gene is responsible for amyotrophic lateral sclerosis." (PMID 21106127, 2010). "Amyotrophic lateral sclerosis (ALS) is characterised by the presence of genetic mutations in autophagy-related genes, including SQSTM1, OPTN, TBK1, VCP, and C9ORF72, which have been found to be linked to family variants of the illness." (PMID 37760929, 2023). "Therefore, we speculate that the OMM proteins are further ubiquitinated by activated Parkin and recruit mitophagy receptors, including the amyotrophic lateral sclerosis (ALS)-associated protein optineurin (OPTN), NDP52, and TAX1BP1, to a similar extent in control or CPZ-treated cells." (PMID 37745295, 2023). "OPTN and TBK1 mutations have also been identified in patients with amyotrophic lateral sclerosis (ALS)." (PMID 36099048, 2022). "Mutations in optineurin (OPTN) have been identified mostly in familial and sporadic cases of amyotrophic lateral sclerosis (ALS)." (PMID 34093394, 2021). "OPTN is present in protein inclusions observed in various neurodegenerative diseases including amyotrophic lateral sclerosis (ALS), Huntington’s, Alzheimer’s, Parkinson’s, Creutzfeld-Jacob’s, and Pick’s disease." (PMID 33114389, 2020). "Optineurin is a gene associated with normal tension glaucoma (NTG) and amyotrophic lateral sclerosis (ALS)." (PMID 24683533, 2014). "Gene mutations in both OPTN and TBK1 have been found in patients suffering from amyotrophic lateral sclerosis (ALS) and frontotemporal dementia (FTD), suggesting physiological and molecular links between OPTN and TBK1." (PMID 38287189, 2024). "OPTN mutations were shown in several familial diseases and often occur in its autophagy-associated ubiquitin-binding domain (UBAN), such as OPTNE478G in amyotrophic lateral sclerosis (ALS) and OPTNR545Q in normal-tension glaucoma." (PMID 35476671, 2022). "Mutations in optineurin (OPTN) are linked to neurodegenerative diseases such as normal tension glaucoma (NTG) and amyotrophic lateral sclerosis." (PMID 41756461, 2026). "Amyotrophic lateral sclerosis (ALS) and frontotemporal dementia share genetic disruptions (for example, C9orf72, OPTN, VCP, TMEM106B and progranulin (PGRN)) that impair normal Golgi–endolysosomal trafficking, severely reducing intracellular protein handling and degradation capabilities." (PMID 41254240, 2025). "More than 90 distinct mutations in TBK1 are linked to amyotrophic lateral sclerosis (ALS) and fronto-temporal dementia, including missense mutations that disrupt the abilities of TBK1 to dimerize, associate with the mitophagy receptor optineurin (OPTN), autoactivate, or catalyze phosphorylation." (PMID 34099552, 2021). "The importance of mitophagy in the pathogenesis of neurodegenerative diseases is supported by the identified mutations of proteins involved in mitophagy—primarily PINK1 and parkin in Parkinson’s disease, optineurin and TBK1 in amyotrophic lateral sclerosis, and p62/SQSTM1 in frontotemporal dementia." (PMID 34638589, 2021). "Also, in amyotrophic lateral sclerosis (ALS) and frontotemporal lobar degeneration (FTLD), the toxic aggregation of one protein – TDP-43 – can result from defects in other proteins, some of which are related to proteostasis, such as the shuttle protein Optineurin and the E3 ubiquitin ligase VCP." (PMID 40969213, 2025).
primary open-angle glaucoma (60 papers, 2007 to 2025). "Roughly 4% of fALS cases and 0.4% of sALS cases carry the OPTN gene mutation, which also causes several other genetic diseases including primary open-angle glaucoma (POAG), Crohn’s disease, and Paget’s disease." (PMID 38178841, 2023). "The authors of the study found only three benign polymorphisms, which were identified in MYOC and OPTN in patients with primary open-angle glaucoma (POAG) and in control subjects." (PMID 22355250, 2012). "Recent studies revealed that optineurin genetic mutation and single nucleotide polymorphisms (SNPs) were associated with open angle glaucoma." (PMID 22194658, 2011). "The original report identified OPTN variants in over 16% of families with open-angle glaucoma." (PMID 39456800, 2024). "Moreover, polymorphisms in the OPTN gene (which mediates mitophagy) are associated with open-angle glaucoma (OAG) with normal lOP (NTG) and younger age of onset of HTG." (PMID 37566048, 2023). "Also, more recent evidence has shown that mutations resulting from a certain polymorphism in the OPTN gene of wide-angle glaucoma patients resulted in the creation of putative CPE binding sites." (PMID 18682811, 2008). "Moreover, the E478G mutation resulted in a puncta-like aggregated distribution, differing from the dispersed cytoplasmic distribution of wild-type OPTN or a primary open-angle glaucoma (POAG) mutation." (PMID 38201303, 2024). "For example, specific genes, such as CYP1B1, which is linked to primary congenital glaucoma, and MYOC, OPTN, and TBK1, which are associated with primary open-angle glaucoma (POAG), are highlighted as critical markers for assessing genetic risk." (PMID 39840199, 2024). "Mutations of optineurin (OPTN) and myocilin (MYOC) genes were associated with the enhanced apoptosis of RGCs in patients with open-angle glaucoma." (PMID 31949441, 2019). "Linkage studies of familial and congenital glaucoma have shown the existence of genes with a significant effect on the disease, such as MYOC (myocilin) and OPTN (optineurin) for familial primary open-angle glaucoma (POAG) and CYP1B1 for congenital glaucoma." (PMID 38333055, 2024). "OPTN, initially identified as a gene responsible for primary open-angle glaucoma (POAG), has a similar domain organization to that of NEMO, although it does not interact with IKKα/β." (PMID 32403254, 2020). "The optineurin gene, OPTN, has been identified as a causative gene of adult-onset primary open-angle glaucoma (POAG) and was named after optic neuropathy-inducing protein." (PMID 24983867, 2014). "This study was designed to evaluate the involvement of the CYP1B1, MYOC, OPTN, and OPTC genes in the etiology of adult-onset primary open-angle glaucoma (POAG) found in 251 Indian patients." (PMID 17563717, 2007).
normal tension glaucoma (34 papers, 2007 to 2026). "An autosomal dominant form of normal tension glaucoma is linked to mutations in OPTN, and mice transgenic for E50K, the most common mutation in normal tension glaucoma, showed altered mitophagy and mitochondrial fission." (PMID 34366851, 2021). "Optineurin (OPTN), which has been principally associated with normal tension glaucoma, is a possible participant in membrane repair because it has been linked to membrane trafficking." (PMID 29682502, 2018). "Several mutations in optineurin have been identified that are associated with normal tension glaucoma." (PMID 24752605, 2014). "Optineurin was found to be linked in particular to normal tension glaucoma (NTG), a subtype of POAG." (PMID 24683533, 2014). "Among them, optineurin is linked principally to normal pressure or normal tension glaucoma, a subtype of POAG." (PMID 20161783, 2010). "One of the candidate genes, optineurin, is linked principally to normal tension glaucoma, a subtype of POAG." (PMID 20161783, 2010). "The gene coding for optineurin has been sequenced and associated with a minority of patients with normal-tension glaucoma." (PMID 19091064, 2008). "Defects in OPTN have been clearly implicated in normal tension glaucoma (NTG), but its role in high-pressure glaucoma has been a source of controversy." (PMID 17615537, 2007). "Certain missense mutations in the gene OPTN cause normal tension glaucoma." (PMID 24752605, 2014). "In addition, mutations of optineurin (OPTN) were known to associated with normal tension glaucoma." (PMID 34980273, 2022). "Mutations in OPTN (optineurin) and TBK1 (TANK-binding kinase 1) genes, have been associated to normal tension glaucoma, which give rise to glaucomatous neurodegeneration in the absence of increased IOP." (PMID 37034386, 2023). "As a gene associated with normal tension glaucoma (NTG), OPTN was recently identified in NFTs and dystrophic neurites in AD patients, suggesting a new role for OPTN in the disease." (PMID 34861878, 2021). "Certain missense mutations in optineurin/OPTN and amplification of TBK1 are associated with normal tension glaucoma." (PMID 26376340, 2015). "Both optineurin (OPTN) and TANK-binding protein 1 (TBK1) have been genetically linked to patients with normal tension glaucoma." (PMID 24699552, 2014). "A potential role of Optineurin (OPTN) when it was first established in 1998 as a second gene in linkage to normal tension glaucoma in the GLCE1 region at locus p15–14 on chromosome 10." (PMID 22690120, 2012). "Mutations in the myocilin gene (MYOC) at GLC1A primarily cause high-tension glaucoma (HTG), and the optineurin gene (OPTN) at GLC1E appears to contribute to normal-tension glaucoma (NTG)." (PMID 19347049, 2009). "Common variants of OPTN, PARL, MFN1 and MFN2 should be analysed in other cohorts to confirm their involvement in normal tension glaucoma." (PMID 19754948, 2009). "The OPTN gene locus was mapped to chromosome 10p15-p14 by linkage analysis of the gene in a large British family with a classic form of normal tension glaucoma." (PMID 18385781, 2008). "The optineurin (OPTN) gene, located at the GLC1E locus on chromosome 10p14-p15, has been shown to cause normal tension glaucoma (NTG), a subtype of POAG." (PMID 17563717, 2007). "Notably, a recent study reported that C-terminal truncation of optineurin (Optn470T), when restricted to glutamatergic neurons, led to both normal-tension glaucoma and ALS-like symptoms in young adult mice." (PMID 41226491, 2025). "An E50K mutation in the Optineurin (OPTN) gene is a leading cause of normal-tension glaucoma (NTG), which directly affects RGCs in the absence of high intraocular pressure and causes severe glaucomatous symptoms in patients." (PMID 34127652, 2021). "Importantly, mutations in OPTN, and a gene duplication of TBK1 leading to increased expression, have been linked to normal tension glaucoma." (PMID 24699552, 2014).
normal tension glaucoma (continued). "OPTN, TBK1, and METTL23 are responsible for early onset normal-tension glaucoma with autosomal dominant inheritance, characterized by significant optic atrophy despite normal IOP." (PMID 38671671, 2024).
frontotemporal dementia (24 papers, 2014 to 2025). Frontotemporal dementia (FTD) comprises a group of neurodegenerative disorders, characterized by progressive changes in behavior, executive dysfunction and language impairment, as a result of degeneration of the medial prefrontal and frontoinsular cortices. "Furthermore, in addition to the ALS phenotype, some patients with OPTN mutations may present with extrapyramidal symptoms, aphasia, or frontotemporal dementia (FTD)." (PMID 38178841, 2023). "TANK-binding kinase 1 (TBK1) phosphorylates SQSTM1 and OPTN, and haploinsufficiency of TBK1 is associated with both ALS and frontotemporal dementia (FTD)." (PMID 37307819, 2024). "To date, a number of disease-associated mutations, specifically in ALS and frontotemporal dementia (FTD), have been identified that perturb TBK1 binding with optineurin, resulting in dysfunction of trafficking pathways such as autophagy." (PMID 29867991, 2018). "Intriguingly, a significant number of genes involved in the pathogenesis of PDB (namely SQSTM1, VCP, PFN1, and OPTN) have been also associated with neurodegenerative disorders (e.g., ALS or frontotemporal dementia) suggesting shared pathophysiological mechanisms." (PMID 36035996, 2022). "For example, several genes causing ALS and/or frontotemporal dementia (C9orf72, VCP, SQSTM1, OPTN, UBQLN2, GRN, CHMP2B) affect the autophagic machinery; and some Alzheimer’s Disease genes (APOE, TREM2, CD33, ABCA7) are preferentially or exclusively expressed in microglia." (PMID 33892821, 2021). "Our study aims to evaluate the genetic and phenotypic spectrum of Frontotemporal dementia (FTD) gene variant carriers in Chinese populations, investigate mutation frequencies, and assess the functional properties of TBK1 and OPTN variants." (PMID 38872230, 2024). "Similar to OPTN, TBK1 has been linked to familial forms of normal tension glaucoma, and ALS combined with frontotemporal dementia (FTD)." (PMID 34201955, 2021). "Up to 15% of ALS patients also develop signs of frontotemporal dementia (FTD) and several genes, including C9ORF72, TDP-43, VCP, SQSTM1, OPTN, UBQLN2 and TBK1, contribute to the etiology of both ALS and FTD." (PMID 37220877, 2023). "Overall, we identified a novel OPTN frameshift insertion in a family with frontotemporal dementia and parkinsonism/CBS but without clinical and neurophysiological evidence of ALS, expanding the phenotypic spectrum of OPTN mutations." (PMID 34093394, 2021).
viral infection (13 papers, 2010 to 2025). "IFNβ overproduction following viral infection was observed not only in several types of optineurin-deficient cell lines but also in Optn-KO mice and human ALS patient cells carrying mutations in OPTN." (PMID 37352136, 2023). "Our in vitro study showed that IFNβ overproduction is induced by viral infection in optineurin-deficient cells, as has been shown previously." (PMID 37352136, 2023). "Our findings indicate that the combination of optineurin deficiency and viral infection leads to IFNβ overproduction in vitro and in vivo." (PMID 37352136, 2023). "Other groups also reported excess IFNβ production in optineurin-deficient fibroblasts during viral infection." (PMID 37352136, 2023). "In this study, we demonstrated that a combination of optineurin deficiency and viral infection induces the overproduction of IFNβ in vitro and in vivo compared with WT controls." (PMID 37352136, 2023). "This study revealed that viral infection of cells deficient in optineurin, sequestosome 1 or NDP52 produce IFNβ excessively." (PMID 37352136, 2023). "It is known that optineurin-deficient cells produce more IFNβ than wild-type cells following viral infection." (PMID 37352136, 2023). "In this context it will be important to determine the response of optineurin deficient mice to virus infection." (PMID 20174559, 2010). "Enterovirus has been detected in the central nervous system of ALS patients; therefore, viral infection of neurons in optineurin-deficient individuals might be a trigger for ALS development." (PMID 37352136, 2023). "In addition, excessive production of IFNβ has been observed in cells and mice with knocked-down OPTN, as well as in patients with OPTN mutations following viral infection." (PMID 38178841, 2023). "However, in this study, viral infection revealed a difference between optineurin-deficient and WT groups with respect to levels of IFNβ production." (PMID 37352136, 2023). "The effects of optineurin deficiency are elicited by viral infection, therefore, viral infection may be implicated in the development of optineurin-related diseases." (PMID 37352136, 2023). "We investigated a possible interaction between optineurin and viral infection in IFNβ production because we previously showed that optineurin inhibits the activities of NF-κB and IRF3." (PMID 37352136, 2023). "Optineurin regulates the expression of interferon beta (IFNβ), which plays a central role in the innate immune response to viral infection." (PMID 37352136, 2023). "IFNβ also enhances optineurin expression following viral infection, whereas optineurin suppresses IFNβ production, suggesting that optineurin negatively regulates IFNβ production following viral infection." (PMID 37352136, 2023). "We demonstrated that a combination of defective optineurin and viral infection leads to excess production of IFNβ in cells and mouse lungs, resulting in increased survival rates of animals following viral infection." (PMID 37352136, 2023). "Optineurin (OPTN) is a conserved autophagy receptor with little understanding of its role in neurotropic viral infections." (PMID 34518549, 2021). "Journo and its co-workers had already described the translocation of NF-κB into the nucleus due to an increase in OPTN expression, but upon a virus infection." (PMID 29782529, 2018). "Immunoprecipitation experiments demonstrated that NS3 binds to OPTN and, in cells expressing NS3, the association between OPTN and TBK1 was impaired after viral infection, accounting for the lower levels of TBK1 activation observed." (PMID 27538435, 2016). "This study demonstrates that the Nemo-related protein optineurin helps to regulate the levels of IFNβ in response to virus infection." (PMID 20174559, 2010). "We have now established that virus infection also markedly increases the amount of optineurin protein present in the cells directly as optineurin expression in cells unable to respond to IFN was still up-regulated by virus infection." (PMID 20174559, 2010).